CGB7 (chorionic gonadotropin subunit beta 7)
Description:
Beta subunit of the human chorionic gonadotropin (hCG). hCG is a complex glycoprotein composed of two glycosylated subunits alpha and beta which are non-covalently associated. The alpha subunit is identical to those in the pituitary gonadotropin hormones (LH, FSH and TSH). The beta subunits are distinct in each of the hormones and confer receptor and biological specificity. Has an essential role for pregnancy and maternal adaptation. Stimulates the ovaries to synthesize the steroids that are essential for the maintenance of pregnancy.
Synonyms: CG-beta-a; CGB6
Tractability: Antibody: UniProt places it where antibodies can reach, with high confidence; UniProt predicts a signal peptide or a membrane-spanning region; its Gene Ontology location is reachable by antibodies, with medium confidence.
Gene: Protein-coding gene on chromosome 19 (49,054,274 to 49,058,860, reverse strand). Ensembl gene ENSG00000196337.
Subcellular location: Secreted
Gene Ontology:
Molecular function: hormone activity
Biological process: apoptotic process; cell-cell signaling; female gamete generation; G protein-coupled receptor signaling pathway; signal transduction; cell communication; signaling
Cellular component: extracellular region
Genetic constraint (gnomAD): Loss-of-function variants: 6 observed, 5.45 expected, observed/expected ratio (o/e) 1.1, 90% interval 0.59 to 1.84. That is too few expected variants to judge how well the gene tolerates losing a copy. Missense variants: 102 observed, 142.39 expected, observed/expected ratio (o/e) 0.72, 90% interval 0.61 to 0.84. Synonymous variants: 44 observed, 54.99 expected, observed/expected ratio (o/e) 0.8, 90% interval 0.63 to 1.03.
Homologues: Orthologues: macaque CGB8 (81% identical), Drosophila melanogaster Gpb5 (15% identical). Paralogues in human: CGB3 (98% identical), CGB5 (98% identical), CGB8 (98% identical), CGB2 (96% identical), CGB1 (90% identical), LHB (70% identical), TSHB (30% identical), FSHB (26% identical), GPHB5 (22% identical).
Diseases named in the same sentence as CGB7 in open-access papers:
CGB7 is named in the same sentence as 6 diseases in open-access papers, as found by Europe PMC text mining. Sharing a sentence is not in itself a finding about the gene and the disease. The quoted sentences say what the papers report.
breast carcinoma (1 paper, 2017). "Further, human breast cancer tissue samples (n=3831) were analyzed using three cBioportal TCGA data sets, in which the expression levels of CGB5, CGB7 and BRCA1 were available." (PMID 28869585, 2017).
breast invasive carcinoma (1 paper, 2017). "The expression levels of CGB5, CGB7 and BRCA1 from breast invasive carcinoma study (TCGA, Cell 2015) is represented as heat map." (PMID 28869585, 2017).
urothelial bladder cancers (1 paper, 2025). "In particular, CGB genes are expressed in the majority of urothelial bladder cancers, where CGB7 is most frequently expressed and significantly associated with an immunosuppressed tumor microenvironment, including decreased CD8+ T cell infiltration." (PMID 40501795, 2025).
urothelial carcinoma (1 paper, 2025). A malignant neoplasm derived from the transitional epithelium of the urinary tract (urinary bladder, ureter, urethra, or renal pelvis). "In a cohort of advanced urothelial carcinoma patients, CGB7 expression is associated with reduced CD8+ T cell infiltration." (PMID 40501795, 2025). "As CGB7 is the most frequently expressed of the CGB genes in our analyses of the TCGA urothelial carcinoma cohort, we elected to focus on CGB7." (PMID 40501795, 2025). "We conclude that CGB7 is significantly associated with blunted interferon gamma signaling and is specifically and significantly associated with decreased CD8+T cell infiltration in the urothelial carcinoma cohorts investigated." (PMID 40501795, 2025). "We therefore sought to further explore the expression pattern of CGB7 in urothelial carcinoma." (PMID 40501795, 2025). "We first wondered how frequently CGB7 is coexpressed with CGB3, CGB5, CGB8, and CGA in urothelial carcinoma." (PMID 40501795, 2025). "To interrogate the possible functional effects of CGB7 expression in cancer, we re-analyzed RNA-sequencing data from the TCGA primary urothelial carcinoma cohort by comparing the gene expression profiles of CGB7-positive and CGB7-negative tumors." (PMID 40501795, 2025). "Further evaluation of expression of these genes in the TCGA urothelial carcinoma cohort revealed that while tumors tend to co-express CGB3, CGB5, and CGB8, CGB7-expressing tumors cluster independently, suggesting that CGB7 is less frequently co-expressed with CGB3, CGB5, and CGB8." (PMID 40501795, 2025).
cancer (2 papers, 2022 to 2025). A tumor composed of atypical neoplastic, often pleomorphic cells that invade other tissues. "Further work will be required to validate CGB7 as a pan-cancer biomarker by confirming associations between CGB7 expression and immunosuppressive signatures in other cancer types, and ultimately by validating this association between CGB7 expression and ICI response in patient samples." (PMID 40501795, 2025). "Here, we systematically assess expression of CGB genes across diverse cancer types and reveal that all CGB genes are pervasively expressed across many cancer types, including urothelial cancer, with CGB7 most frequently expressed." (PMID 40501795, 2025). "Of the four CGB genes, CGB7 is expressed most frequently across cancer types and in urothelial cancer." (PMID 40501795, 2025). "We focused these and prior analyses on CGB7 because CGB7 is more commonly expressed than other CGB genes in this cancer type." (PMID 40501795, 2025). "Comparing expression of each CGB gene in tumor and matched normal peritumoral tissues across these datasets elucidated extensive cancer-specific expression of CGB3, CGB5, CGB7, and CGB8 across cancer types." (PMID 40501795, 2025). "We sought to systematically evaluate the expression patterns of each functional CGB gene (CGB3, CGB5, CGB7, and CGB8) across 20 distinct cancer types utilizing gene expression data from The Cancer Genome Atlas (TCGA)." (PMID 40501795, 2025). "Numerous studies have demonstrated that beta-hCG-encoding genes are expressed in various cancers, but expression of these genes (CGB3, CGB5, CGB7, and CGB8) across diverse cancers has not been systematically evaluated." (PMID 40501795, 2025).
tumor (1 paper, 2025). "Taken together, we conclude that CGB7 expression is strongly associated with an immunosuppressive tumor microenvironment and decreased overall survival probability, suggesting a role of CGB7 in immune escape of tumors." (PMID 40501795, 2025). "Overall, these findings reinforce our hypothesis that CGB7 is consistently associated with an immunosuppressive tumor microenvironment and hallmarks of immune escape." (PMID 40501795, 2025). "Taken together, our data suggest that CGB7 may facilitate the conversion of the tumor microenvironment to an immunosuppressive state." (PMID 40501795, 2025). "As interferon gamma facilitates tumor infiltration of CD8+ T cells and is ultimately a marker of CD8+ T cell activity, we next investigated whether CGB7 expression affects CD8+ T cell infiltration using immune phenotype classification data for tumor samples from the IMVigor 210 cohort." (PMID 40501795, 2025).